RN7SKP43 (RN7SK pseudogene 43)
Gene: Miscellaneous RNA gene on chromosome 2 (217,251,556 to 217,251,875, forward strand). Ensembl gene ENSG00000251982.
Homologues: Orthologues: chimpanzee 7SK (90% identical), guinea pig 7SK (33% identical), mouse Gm56014 (33% identical). Paralogues in human: RN7SKP124 (48% identical), RN7SKP192 (48% identical), 7SK (47% identical), RN7SKP180 (47% identical), RN7SKP79 (47% identical), RN7SKP146 (47% identical), RN7SKP189 (47% identical), RN7SKP90 (47% identical), RN7SKP217 (46% identical), RN7SKP93 (46% identical), RN7SKP149 (46% identical), RN7SKP250 (46% identical), and 284 more.